ENSG00000207171
Synonyms: LOC124900181
Gene: Small nucleolar RNA gene on chromosome 4 (168,471,409 to 168,471,539, forward strand). Ensembl gene ENSG00000207171.
Gene Ontology:
Biological process: RNA processing
Cellular component: nucleolus
Homologues: Orthologues: rat LOC120097227 (58% identical). Paralogues in human: SNORA51 (91% identical).